DDIT3 (DNA damage inducible transcript 3)
Diseases named in the same sentence as DDIT3 in open-access papers (continued):
Sharing a sentence is not in itself a finding about the gene and the disease.
COVID-19 (7 papers, 2020 to 2025). A disease caused by infection with severe acute respiratory syndrome coronavirus 2. "As shown in the UMAP and violin plots, in COVID-19 patients, DDIT3 was highly expressed in neutrophils and cDC cells, MAFF was highly expressed in neutrophils and GZMK NK cells, and PNRC1 was highly expressed in almost all immune cells and blood cells." (PMID 37283761, 2023). "In the present study, we succeeded in identifying 3 key genes, DDIT3, MAFF, and PNRC1, which are possibly involved in the development of both OA and COVID-19 and have high diagnostic value for OA and COVID-19." (PMID 37283761, 2023). "Similarly, we found the relevant evidence of alteration or association of transcription factors CENPA, DDIT3, JUNB, TFDP1, ZBTB16, ZNF467 for the alteration of diverse cellar process and function to develop the COVID-19 pathogenesis and associated respiratory disorders." (PMID 38365632, 2024). "Intriguingly, within these networks, certain molecular entities (RELB, DDIT3, and FOSL1) were identified as hub genes with increased expression in our patient samples during the 1-year follow-up after severe COVID-19." (PMID 39205185, 2024). "In this study, we identified 26 common genes between OA and COVID-19 by WGCNA and screened three key genes DDIT3, MAFF, and PNRC1 using machine learning algorithms." (PMID 37283761, 2023). "Collectively, these results suggest that DDIT3, MAFF, and PNRC1 play important roles in OA and COVID-19 pathogenesis, while STX11 lacks specificity." (PMID 37283761, 2023). "The gene expression and functional analysis of the early vs. late COVID-19 cases revealed significant differences with increased levels of ADAM17, C1S, SERPING1, and DDIT3 in the early group." (PMID 35163504, 2022). "In addition, we screened 3 key genes, DDIT3, MAFF, and PNRC1, and uncovered that key genes are possibly involved in the pathogenesis of OA and COVID-19 through high expression in neutrophils." (PMID 37283761, 2023). "Comparing the results of the analysis with those of the HPA database, we found that the expression of DDIT3, MAFF, and PNRC1 in immune cells was the same as normal, indicating that the expression pattern of key genes in immune cells did not change during the progression of COVID-19." (PMID 37283761, 2023).
mesothelioma (7 papers, 2010 to 2022). A usually malignant and aggressive neoplasm of the mesothelium which is often associated with exposure to asbestos. "It is also reported that DDIT3 expression is suppressed by STAT3, leading to enhanced survival in mesothelioma." (PMID 29914181, 2018).
thyroid cancer (7 papers, 2018 to 2025). "Metformin was discovered to upregulate heat shock protein family A member 5 (HSPA5, Bip), DNA damage-inducible transcript 3 (DDIT3, CHOP), and caspase-12 and induce endoplasmic reticulum stress and endoplasmic reticulum stress-associated apoptosis in vitro and in vivo in thyroid cancer." (PMID 37344841, 2023).
anemia (6 papers, 2022 to 2025). A reduction in the number of red blood cells, the amount of hemoglobin, and/or the volume of packed red blood cells. "We also detected improved erythroid differentiation upon DDIT3 knockdown in CD34+ cells of four additional MDS cases showing anemia." (PMID 36494342, 2022). "All together, these results suggest that inhibition of DDIT3 in patients with MDS presenting anemia restores proper terminal erythroid differentiation." (PMID 36494342, 2022). "The fact that knockdown of DDIT3 in CD34+ cells from MDS cases restores erythroid differentiation, suggests that DDIT3 could represent a potential therapeutic target for the treatment of patients, particularly those with anemia." (PMID 36494342, 2022). "Moreover, DDIT3 knockdown in CD34+ cells from MDS patients with anemia is able to restore erythropoiesis." (PMID 36494342, 2022).
Allergy (5 papers, 2018 to 2022). An allergy is an immune response or reaction to substances that are usually not harmful. "In contrast, the unique genes in the OTM group included Ddit3, Il1r2, Mmp9, Stfa2, and Stfa3, with the distinguishing feature of ‘allergy’ and ‘endopeptidase regulation’, which revealed the activation of macrophages after OTM." (PMID 35185928, 2022).
astrocytoma (5 papers, 2011 to 2024). "The transcriptomic analysis shows that the components of the UPR-related genes such as PERK, ATF4, and DDIT3 (encoded CHOP) and early growth response 1 (EGR1) are activated in VEEV-infected human astrocytoma cells." (PMID 37946006, 2024).
Cirrhosis (5 papers, 2013 to 2025). A chronic disorder of the liver in which liver tissue becomes scarred and is partially replaced by regenerative nodules and fibrotic tissue resulting in loss of liver function. "Both ATF4 and DDIT3 mRNA expression were significantly increased in samples of patients with HCV-related cirrhosis, where HCV viral load is fluctuating compared to the tumor tissue of patients with HCV-associated HCC where HCV viral load decrease." (PMID 32283772, 2020). "The increased expression of ATF4 and DDIT3 was specific for HCV-related cirrhosis since their expression was not induced in liver samples of patients with non-HCV end-stage liver disease as HBV-associated cirrhosis." (PMID 32283772, 2020).
cardiomyopathy (4 papers, 2017 to 2024). A disease of the heart muscle or myocardium proper. "Genes associated with ER stress (e.g., ATF4, NUPR1, DDIT3, TRIB3, CHAC1, SESN2, HERPUD1) were upregulated and genes related to cardiomyopathy and sarcomeric structure (e.g., MYH7, SYNPO2L, LDB3, ACTN2, MYLK3) were downregulated by afatinib, sorafenib, or high-dose ponatinib." (PMID 37069550, 2023).
chronic obstructive pulmonary disease (4 papers, 2022 to 2025). A chronic and progressive lung disorder characterized by the loss of elasticity of the bronchial tree and the air sacs, destruction of the air sacs wall, thickening of the bronchial wall, and mucous accumulation in the bronchial tree. "We validated some key genes by real-time PCR and found Decr1 (an enzyme which participates in fatty acid β-oxidation), Calm2 (associated with cardiac arrhythmias), and Ddit3 (a proapoptotic transcription factor) expressed a statistically significant increase when compare with the control group." (PMID 35464763, 2022). "In turn, the inhibition of the two interactions of DDIT3 identified by MuXTalk, CUL1 and EP300, has been shown to reduce fibroblast proliferation in chronic obstructive pulmonary disease (COPD) and IPF." (PMID 37953325, 2024).
diabetic retinopathy (4 papers, 2016 to 2025). "Jun and Ddit3 signaling have been shown to be involved in other injuries to RGCs including ischemic injury, diabetic retinopathy, and traumatic optic neuropathy (and traumatic brain injury)." (PMID 28969695, 2017).
intracerebral hemorrhage (4 papers, 2022 to 2024). A cerebrovascular disorder characterized by bleeding into one or both cerebral hemispheres including the basal ganglia and the cerebral cortex. "Studies have shown that Atf4 can increase the expression of the transcriptional activator Ddit3, thereby promoting apoptosis and reducing neuronal survival after intracerebral hemorrhage." (PMID 36497037, 2022).
Osteopenia (4 papers, 2013 to 2024). Osteopenia is a term to define bone density that is not normal but also not as low as osteoporosis. "In contrast, the osteogenic differentiation of MC3T3-E1 cells was enhanced by reducing the expression of DDIT3; furthermore, DDIT3 transgenic mice, driven by osteocalcin promoter, displayed a phenotype characterized by osteopenia." (PMID 39331002, 2024). "The osteogenic markers were improved after being treated with 4-phenyl butyric acid (4-PBA, an ER stress inhibitor); the functionality of osteoblast was diminished, resulting in the development of osteopenia in DDIT3 transgenic mice." (PMID 39331002, 2024).
pancreatitis (4 papers, 2021 to 2024). Inflammation of the pancreas. "There was no appreciable difference between CPA1 N256K and CPA1 N256K × Ddit3-KO mice, indicating similar severity of pancreatitis." (PMID 35428786, 2022). "We found that Nfic inactivation does not result in increased damage upon induction of a mild pancreatitis, but it impairs homeostatic recovery, with sustained up-regulation of Ddit3/Chop and Hsp17b1 in Nfic-/- pancreata, indicating enhanced ER stress." (PMID 37353485, 2023).
Atrophy (3 papers, 2022 to 2025). Any weakening or degeneration, especially through lack of use. "The findings indicate that genetic deletion of Ddit3/Chop in the CPA1 N256K mice does not protect against onset and progression of chronic pancreatitis, as judged by pancreatic atrophy." (PMID 35428786, 2022).
autoimmune disease (3 papers, 2018 to 2019). A disorder resulting from loss of function or tissue destruction of an organ or multiple organs, arising from humoral or cellular immune responses of the individual to their own tissue constituents. "The Ddit3 and Hspa5 results are especially intriguing as depletion of DDIT3 has been shown to exacerbate disease in PMD animal models, while reduction of HSPA5 is deleterious to oligodendrocyte survival in both normal and autoimmune disease contexts and is depleted in PMD models." (PMID 30146490, 2018).
chondrosarcoma (3 papers, 2017 to 2024). A malignant cartilaginous matrix-producing mesenchymal neoplasm arising from the bone and soft tissue. "Overall, the prognostic model based on single-cell signature indicated DDIT3/CHOP as an early marker for chondrosarcoma." (PMID 38267611, 2024).
dementia (3 papers, 2018 to 2024). Loss of intellectual abilities interfering with an individual's social and occupational functions. "We identified altered proteins in AD not common to other dementias like the E3 ubiquitin-protein ligase TOPORS, Layilin and MICB, and validated the association to AD of the previously controverted proteins DDIT3 and the E3 ubiquitin-protein ligase XIAP." (PMID 29541381, 2018).
kidney stone (3 papers, 2024 to 2025). "This activation of DDIT3 might contribute to the initiation of cell apoptosis, which may facilitate CaOx crystal adhesion and exacerbate kidney stone formation." (PMID 39452083, 2024).
lipoblastoma (3 papers, 2020 to 2025). A lipoma usually occurring in the extremities of young children (usually boys). "An initial excisional biopsy confirmed a lipoblastoma-like tumor, characterized by spindle cells in a myxoid stroma, focal positivity for CD34 and S100, and absence of DDIT3 rearrangement." (PMID 41246635, 2025).
mesenchymal neoplasm (3 papers, 2021 to 2026). "The amplification of DDIT3 and STAT6 may vary depending on the amplicon length in cases of mesenchymal neoplasms with 12q13-15 amplification." (PMID 38275873, 2024).
myeloid leukemia (3 papers, 2014 to 2024). A clonal proliferation of myeloid cells and their precursors in the bone marrow, peripheral blood, and spleen. "The suppression of SEC61A1 and SEC61B has been observed to stimulate Ddit3 expression in myelogenous leukemia cells." (PMID 39000233, 2024).
spinal cord injury (3 papers, 2014 to 2023). Penetrating and non-penetrating injuries to the spinal cord resulting from traumatic external forces (e.g., WOUNDS, GUNSHOT; WHIPLASH INJURIES; etc.). "The integrated stress response (ISR)-activated transcription factors ATF4 and CHOP/DDIT3 may regulate oligodendrocyte (OL) survival, tissue damage and functional impairment/recovery in white matter pathologies, including traumatic spinal cord injury (SCI)." (PMID 37280306, 2023).
thyroid (3 papers, 2011 to 2024). "Except for three thyroid samples, all thyroid tumor tissue samples from thyroid tissue from the two groups and all histology types tested positive for malignancy with antibodies C1orf24, ITM1, and DDIT3 and negative PVALB." (PMID 31067756, 2019).
acute pancreatitis (2 papers, 2021 to 2022). An acute inflammatory process that leads to necrosis of the pancreatic parenchyma. "The papers report somewhat more severe disease in the knockout strain, indicating a possible protective role of DDIT3/CHOP in acute pancreatitis." (PMID 35428786, 2022).
adenoma (2 papers, 2009 to 2021). A neoplasm arising from the epithelium. "The tumor suppressive effects of ferrichrome were confirmed through the upregulation of DDIT3 in patient-derived organoids of adenoma and carcinoma." (PMID 33407519, 2021). "Damage-inducible transcript 3 (DDIT3) and arginase II (ARG2) showed a high specificity with 85% positivity in carcinomas and only 9,4% positivity in adenomas." (PMID 19321014, 2009).
Chronic Myeloid Leukemia (2 papers, 2010 to 2022). "Aberrant methylation was found in the DDIT3 gene promoter in patients with chronic myeloid leukemia (CML)." (PMID 36422902, 2022).
chronic pancreatitis (2 papers, 2022 to 2025). A chronic inflammatory process causing damage and fibrosis of the pancreatic parenchyma. "Here, we crossed the CPA1 N256K strain with mice containing a global deletion of the Ddit3/Chop gene (Ddit3-KO mice) and evaluated the effect of DDIT3/CHOP deficiency on the course of chronic pancreatitis." (PMID 35428786, 2022). "In the present study, we generated a CPA1 N256K strain with a global deletion of Ddit3/Chop, and studied the effect of DDIT3/CHOP deficiency in the development and course of chronic pancreatitis." (PMID 35428786, 2022). "Surprisingly, CPA1 N256K x Ddit3-KO mice developed chronic pancreatitis with a similar time course and features as the CPA1 N256K parent strain." (PMID 35428786, 2022). "At the onset of these studies, we assumed that acinar cell death would play a key role in the fibro-inflammatory process and protection against acinar cell death by deletion of Ddit3/Chop would prevent the development and/or progression of chronic pancreatitis." (PMID 35428786, 2022). "In this study, we demonstrate that the transcription factor DDIT3/CHOP plays no significant role in the onset, progression and severity of chronic pancreatitis in CPA1 N256K mice harboring a misfolding CPA1 variant." (PMID 35428786, 2022). "Taken together, the observations indicate similar severity of chronic pancreatitis in CPA1 N256K and CPA1 N256K × Ddit3-KO mice with respect to macrophage infiltration, acinar-to-ductal metaplasia, and fibrosis." (PMID 35428786, 2022). "Despite these potential shortcomings, the conclusions of the study are straightforward and rule out DDIT3/CHOP as a potential therapeutic target in misfolding-induced chronic pancreatitis." (PMID 35428786, 2022). "The observations indicate that DDIT3/CHOP plays no significant role in the development of misfolding-induced chronic pancreatitis in CPA1 N256K mice and this transcription factor is not a viable target for therapeutic intervention in this disease." (PMID 35428786, 2022).
colon adenocarcinoma (2 papers, 2011 to 2025). "A combination survival analysis revealed that patients with a high co-expression of ULBP1, AARS1, and DDIT3 exhibited a 2.2-fold increased risk of death from colon adenocarcinoma (COAD) compared to patients with a low expression of all three genes." (PMID 41008630, 2025).
esophageal cancer (2 papers, 2022 to 2024). A primary or metastatic malignant neoplasm involving the esophagus. "In conclusion, our study provides compelling evidence that ferrichrome exerts potent anti-tumor effects by inducing apoptosis through the DDIT3 pathway in esophageal cancer cells." (PMID 38545201, 2024). "Our findings indicate that ferrichrome induces DNA damage-inducible transcript-3, thereby producing anti-tumor effects, including cell cycle arrest and apoptosis, with minimal adverse effects in esophageal cancer cells." (PMID 38545201, 2024). "Similarly, in esophageal cancer cells, ferrichrome displayed an anti-tumor activity by promoting DDIT3-mediated apoptosis." (PMID 38545201, 2024). "Therefore, we sought to determine whether ferrichrome could also induce DDIT3 expression in esophageal cancer cells." (PMID 38545201, 2024). "Furthermore, DDIT3 overexpression can promote esophageal cancer cell apoptosis." (PMID 38545201, 2024).
influenza (2 papers, 2015 to 2024). An acute viral infection of the respiratory tract, occurring in isolated cases, in epidemics, or in pandemics; it is caused by serologically different strains of viruses (influenzaviruses) designated A, B, and C, has a 3-day incubation period, and usually lasts for 3 to 10 days. "Several other pro-apoptotic genes including TNFRSF12A, DDIT3, and CDKN1A were upregulated in SUS animals, indicating that they may also contribute to apoptotic events during influenza infection in swine." (PMID 26393920, 2015).
kidney cancer (2 papers, 2020 to 2022). Primary or metastatic malignant neoplasm involving the kidney. "Furthermore, high levels of ISR effectors DDIT3 and ATF4 correlated with shortened patient survival in Mic60-low GBM and kidney cancer but not Mic60-high BRCA and LUAD." (PMID 35177476, 2022).
lipoma (2 papers, 2014 to 2015). A benign, usually painless, well-circumscribed lipomatous tumor composed of adipose tissue. "The lipomas contained large subpopulations expressing DDIT3." (PMID 24790523, 2014). "Break apart of DDIT3 was confirmed in each MLS regardless of lipoma-like changes." (PMID 25650275, 2015). "They considered that the presence of microscopic foci of lipoma-like or sclerosing areas, characteristic of WDLS, constitutes sufficient histologic evidence to exclude the diagnosis of MLS, as supported by the consistent absence of DDIT3 or FUS genomic rearrangements in such tumors." (PMID 25650275, 2015).
malignant pleural mesothelioma (2 papers, 2016 to 2023). A malignant neoplasm that arises from mesothelial cells in the pleura and shows a diffuse growth pattern. "Suppression of DDIT3 mRNA upregulation has been shown to be involved in chemoresistance of malignant pleural mesothelioma cells, further suggesting that multiple mechanisms may play a role in HE4-mediated chemoresistance." (PMID 27184254, 2016). "Similarly, in malignant pleural mesothelioma, the STAT3- nuclear factor-kappa B/DNA Damage Inducible Transcript 3/enhancer-binding protein beta (STAT3-NF-kB/DDIT3/CEBPβ) axis was demonstrated to regulate ALDH1A3 expression and reduce sensitivity to pemetrexed + cisplatin treatment." (PMID 36672441, 2023).
prostate adenocarcinoma (2 papers, 2018 to 2024). "The patients with high expression of ASNS and DDIT3 showed worse disease-free survival in patients with The Cancer Genome Atlas (TCGA)-prostate adenocarcinoma (PRAD) datasets." (PMID 38474084, 2024).
Sjögren’s syndrome (2 papers, 2018 to 2022). "To gain further knowledge about the balance between survival and apoptosis signaling factors in Sjögren’s syndrome conjunctiva, we evaluated the expression of the pro-apoptotic factor DDIT3." (PMID 35562919, 2022). "Our study in patients with Sjögren’s syndrome, and a stratified human model of corneal epithelial differentiation, supports these findings and points to the involvement of the pro-apoptotic factor DDIT3 in mediating epithelial cell death." (PMID 35562919, 2022).
thyroid tumor (2 papers, 2011 to 2019). A benign or malignant neoplasm affecting the thyroid gland. "Other groups have also investigated the expression of DDIT3, ITM1 and C1orf24 in thyroid tumors." (PMID 22654558, 2011).
Anorexia (1 paper, 2021). Lack of desire to eat (loss of appetite). "ISR-ATF4/DDIT3-dependent GDF15 regulation may be important in many different diseases and the therapeutic effects of drugs related to anorexia, cancer, and metabolic disorders." (PMID 34877504, 2021).
Autoimmunity (1 paper, 2025). The occurrence of an immune reaction against the organism's own cells or tissues. "Deficiency of DDIT3 ameliorates lupus-like autoimmunity and renal injury by inhibiting the germinal center response and B cell activation." (PMID 40166629, 2025).